APOE (apolipoprotein E)
Diseases named in the same sentence as APOE in open-access papers (continued):
Sharing a sentence is not in itself a finding about the gene and the disease.
Cognitive impairment (continued). "Women who had one copy of the APOE-ε4 allele or who were previously incarcerated had greater risk for cognitive impairment than men with the same background/status." (PMID 38048316, 2023). "In contrast, there is a skewed prevalence for the stratified genotypes among these characteristics, where APOE ε4 carriers associated with cognitive deficits, while APOE ε2 and BIN only associated with age." (PMID 39081475, 2022). "Further, APOE ε4 carriers significantly associated with cognitive deficits (p = 0.038), contrary to ε2 carriers (p = 0.382)." (PMID 39081475, 2022). "The most robust findings have demonstrated that the presence of the APOE ε4 allele imparts a genetic risk for the development of cognitive impairment, specifically that related to AD and vascular dementia." (PMID 35720695, 2022). "Another study reported an opposing role of ApoE-2 allele as a risk factor for cognitive impairment in ALS, signifying a link between cholesterol hypometabolism and neurodegeneration." (PMID 35840315, 2022). "The risk of cognitive impairment among those with the APOE Ɛ4 allele was highest among the moderate and heavy drinkers." (PMID 35275952, 2022). "This study aimed to determine the relationship between COVID-19 and cognitive impairment and APOE gene polymorphisms in an outpatient public university hospital in Northeast Brazil." (PMID 36046159, 2022). "This study provides insights into population-specific risk factors, reinforcing APOE ε4 as a risk factor to cognitive deficits among the Portuguese population." (PMID 39081475, 2022). "APOE ε4 allele carriers are additionally burdened by increased Aβ oligomer levels, which trigger depressive-like behavior as well as cognitive impairment due to an influence on synaptic plasticity." (PMID 35884866, 2022). "As alcohol level increased, the age at incident moderate cognitive impairment decreased, especially among those with at least one APOE Ɛ4 allele." (PMID 35275952, 2022). "The formation of Aβ plaques, Tau hyperphosphorylation, NFT formation, and the onset of neurodegeneration and cognitive impairment in patients with AD have been associated with specific neurotoxic ApoE fragments, such as an 18 kDa N‐terminal fragment." (PMID 35810473, 2022). "This study revealed that the presence of the APOE-ε4 allele was associated with lower body mass in women with cognitive impairment." (PMID 35276898, 2022). "In summary, the results of this study show that the ability of XN to mitigate cognitive impairments associated with consumption of a HFD starting at 6 months of age are apoE isoform- and sex-dependent." (PMID 36278228, 2022). "The results of this study show that the ability of XN to mitigate cognitive impairments in the Y maze associated with consumption of a HFD starting at 6 months of age are apoE isoform- and sex-dependent." (PMID 36278228, 2022). "The vascular factor and apolipoprotein E gene (APOE) ε4 allele are important factors associated with cognitive impairment." (PMID 35847686, 2022). "As alcohol level increased, the age at incident moderate cognitive impairment decreased, especially among those with at least one apolipoprotein E Ɛ4 allele." (PMID 35275952, 2022). "Recently, a higher frequency of APOE ε4 alleles (19.6%) was reported in a population with cognitive impairment from a Chinese memory clinic, which supports our assumption." (PMID 35720695, 2022). "In contrast, sevoflurane anesthesia caused Tau phosphorylation and cognitive impairment in juvenile ApoE‐KO mice." (PMID 35810473, 2022). "APOE-4 carriers tend to show a more severe DNA hypomethylation pattern than patients carrying the APOE-3 allele, which is aggravated in parallel with the degree of cognitive impairment." (PMID 35330211, 2022). "Recent studies on cognitive functions in patients with MTBI have found that cognitive deficits were associated with APOE-ε4 status in this patient group." (PMID 35250800, 2022).
Cognitive impairment (continued). "It is interesting to notice that patients carrying both BuChE-K variant and APOE-ε4 had an earlier onset of cognitive impairment." (PMID 36203811, 2022). "APOE ε4 are associated with memory dysfunction and an increased risk of cognitive and functional decline in people with mild cognitive impairment." (PMID 35160273, 2022). "The possession of the APOE ε4 allele should be performed in the study to predict the risk of progression to AD and to confirm the enrollment criteria of mild cognitive impairment." (PMID 35368763, 2022). "Among respondents with the APOE Ɛ4 allele, even moderate drinking showed an increased risk for subsequent cognitive impairment." (PMID 35275952, 2022). "Further studies involving large datasets with both sexes based on robust statistical evidence are therefore required to elucidate the association between APOE-ε4 and body mass in patients with cognitive impairment." (PMID 35276898, 2022). "As for the cognitive characteristics, our results showed an association between APOE ε4 and cognitive deficits." (PMID 39081475, 2022). "The effect of physical exercise on cognitive performance in older adults is also conditioned or moderated by the presence of apolipoprotein E (ApoE4), a genetic risk factor in cognitive impairment." (PMID 35321640, 2022). "Altogether, our findings support previous studies in other ethnicities, implying a role for APOE ε4 and ε2 as risk and protective factors, respectively, for cognitive impairment in PD." (PMID 36371506, 2022). "Results demonstrated cerebral perfusion as an independent risk factor not only for cognitive impairments but also an important mediator for the effects of APOE genotype on the cognitive deficiency." (PMID 35847686, 2022). "The APOE genotype, level of cognitive impairment, and brain pathological structural damage that underlies each subtype are likely distinct." (PMID 35492717, 2022). "This suggests that there are some larger effect sizes, common variants (i.e. the peaks in the Manhattan plot outside the APOE locus) that are predictive of brain atrophy in persons that already display some cognitive impairment." (PMID 36523268, 2022). "We found a modest but significant (protective) association of the APOE ε2 allele with cognitive status in our cohort, with higher ε2 dosage conferring a lower (but small) risk of self-declared cognitive impairment in individuals with PD." (PMID 36371506, 2022). "Some studies have provided evidence of an association between APOE-ε4 and body mass, for example, body mass index (BMI) in older adults with mild cognitive impairment (MCI) and AD." (PMID 35276898, 2022). "Our results are broadly consistent with those from studies on healthy aging, reporting KL-VShet to be associated with better cognition, and lower risk of conversion from cognitively normal to mild cognitive impairment or AD dementia in ApoE ε4 carriers." (PMID 34158479, 2021). "In supplemental analyses, we presented the associations between single lifestyle factors and cognitive impairment stratified by APOE genotype in S1 Table." (PMID 34061824, 2021). "Many patients (61%) had a first degree family relative with cognitive impairment, and 36% had ≥1 copy of the APOE ɛ4 allele." (PMID 34219723, 2021). "Several studies agreed that ApoE‐ε4 was associated with memory deficit or global cognitive impairment, whereas some stated that ApoE‐ε4 had little effect on cognitive function." (PMID 34555265, 2021). "We evaluated the effect of APOE-ε4 on the cholinergic structural association and the neurocognitive performance for subjects with different levels of cognitive impairment." (PMID 34721251, 2021). "Studies are yet to elucidate how the specific amygdala and basal forebrain subnuclei atrophy relate to cognitive functioning, which is affected by the APOE-ε4 allele at different levels of cognitive impairment." (PMID 34721251, 2021).
Cognitive impairment (continued). "We examined the associations of cognitive impairment with lifestyle profile and APOE genotype using multivariable logistic regressions, controlling for age, sex, education, marital status, residence, disability, and numbers of chronic conditions." (PMID 34061824, 2021). "APOE ɛ4 carriers are at increased risk for cognitive impairment and chronic traumatic encephalopathy following head injury." (PMID 33499167, 2021). "The association between serum ApoA1 or ApoB levels and cognitive impairment in patients with schizophrenia were regulated by the existence of ApoE rs429358 polymorphism." (PMID 34135129, 2021). "In this cross-sectional study of the Chinese oldest old (aged 80 years or older), we assessed the association between APOE ε4 genotype, lifestyle profiles, and cognitive impairment." (PMID 34061824, 2021). "The ApoE gene encodes three alleles, namely ApoE2, ApoE3, and ApoE4It, where ApoE4 is the major genetic risk factor for sporadic AD and is associated with cognitive deficits." (PMID 34204308, 2021). "In our study, a significant association between APOE ε4 genotype and cognitive impairment was found, similar to a previous study among 425 Chinese elderly with an average age of 83 years." (PMID 34061824, 2021). "This suggests that the penetrance of the APOE-ε4 allele influences the rate of cognitive dysfunction and the likelihood of transitioning to mild cognitive impairment (MCI) and AD, which is variable and potentially modifiable." (PMID 34069601, 2021). "In summary, we found that the APOE genotype and lifestyle profiles were independently associated with cognitive impairment." (PMID 34061824, 2021). "There is therefore a need for large longitudinal population studies to examine the long-term prospective risk of APOE*ε4 for depression in which confounding of concurrent cognitive impairment and initial mental health are controlled." (PMID 32381152, 2020). "One study revealed that cognitive impairment was six times higher in patients with the risk factors of low educational level, apolipoprotein E (APOE) ε4 allele, and Herpesviridae, including CMV, infection." (PMID 32466754, 2020). "We applied the generalized estimating equations (GEE) to examine the association between baseline annual average NDVI, APOE ε4 carrier status, and cognitive impairment." (PMID 31919381, 2020). "Model 1 showed that the risk of cognitive impairment of APOE ε4 carriers vs. non-ε4 carriers (OR: 1.15, 95% CI: 1.05, 1.26)." (PMID 31919381, 2020). "Because the APOE ε4 allele had effects on the relationship between serum lipid levels and cognitive impairment, stratified binary logistic regression analyses were performed according to APOE ε4 status." (PMID 32231559, 2020). "They reported that APOE ε4 influences the progression from mild cognitive impairment to AD in all age groups and the risk varies in age, reaching its peak between ages 70 and 75 years and decreasing after the age of 75 years." (PMID 32464432, 2020). "Further studies are needed to explore the effects of chronic toxoplasmosis over cognitive impairment, including AD, in individuals with specific genetic markers (i.e., APOE-ε4) and environmental risk factors." (PMID 32545619, 2020). "This latter study estimated BDNF Met carriers with the APOE ε4 allele would have clinically significant cognitive impairment in 3 years, as compared to 10 years if the individual was an APOE ε4 carrier and BDNF Val homozygote." (PMID 32218234, 2020). "Our findings suggest that APOE ε4 allele carriage has greater effects on cognitive impairment than residential greenness, which was observed only among the older adults aged 65 to 79 years old." (PMID 31919381, 2020). "AD probability decreases in carriers of the e2 variant of the APOE gene (APOE-e2), whereas APOE-e4 is believed to be a strong risk factor and is associated with overall cognitive impairment and synapse loss (see review by Selkoe, 2002)." (PMID 32457598, 2020).
Cognitive impairment (continued). "Our study reinforced the evidence of higher risks of APOE ε4 allele carriage on cognitive impairment, and provided extra evidence on gene-environment interaction." (PMID 31919381, 2020). "Our findings reinforced evidence on the higher risks of APOE ε4 allele carriage on cognitive impairment among older adults." (PMID 31919381, 2020). "In this cross-sectional study, we found a significant interaction effect between low HDL and the APOE ε4 allele on cognitive impairment in the total participants." (PMID 32231559, 2020). "It is well known that APOE ε4 is associated with an increased risk of cognitive impairment (i.e., executive function)." (PMID 32943742, 2020). "Regression models adjusted for APOE genotypes, lipid parameters and other risk factors for cognitive impairment were applied to assess the association between Lp(a) and performance in specific cognitive domains." (PMID 32606300, 2020). "Ninety-nine (7.8%) subjects met the diagnostic criteria of cognitive impairment, and a total of 189 people (14.8%) were APOE ε4 carriers." (PMID 32231559, 2020). "We found that a biomarker-defined CBS-AD group had a milder clinical trajectory, greater ventriculomegaly, higher APOE-ε4 allele frequency, and greater cognitive impairment compared with the CBS-4RT group." (PMID 31860007, 2020). "Apolipoprotein E4 (APOE4) and obesity are independently associated with increased risk of metabolic syndrome and cognitive impairment." (PMID 31554665, 2019). "As memory deficits are considered the major cognitive impairment in AD, the relationship between memory decline and the presence of the APOE ε4 allele in AD was examined a lot." (PMID 30866553, 2019). "Subsequent analysis showed that MHT users with apolipoprotein E (APOE) E4 allele presented worse cognitive impairment." (PMID 31581598, 2019). "If NPTX2 confers resilience, one would predict that risk factors for AD, such as older age, APOE-e4 genotype, and level of CR would be more strongly associated with cognitive impairment or risk of progression to MCI among individuals with low levels of NPTX2." (PMID 31231205, 2019). "ApoE-deficient mice are cognitively impaired and exhibit more severe motor and cognitive deficits after closed head injury." (PMID 31607842, 2019). "The main clinical implication of our findings is that high BG also increases the risk of cognitive impairment, even among the “neutral” APOE ε3/ε3 genotype carriers." (PMID 30984391, 2019). "A previous study also showed that the APOE ε4 allele contributes to the reduction of hippocampal volume in patients with mild cognitive impairment (MCI) and Alzheimer’s disease (AD)." (PMID 30863302, 2019). "Although APOE status does not appear to be associated with PD and findings have been inconsistent regarding PDD, 2 recent studies reported that the APOE ɛ4 allele predicted cognitive deficits in PD." (PMID 31033450, 2019). "Based on the rs7412 SNP, the frequency of the APOE-ε2 allele in patients showing normal cognition vs. cognitive impairment was 14.2 vs. 18.9%." (PMID 31649612, 2019). "Apolipoprotein E polymorphism ε4 allele (ApoE4) is associated with cognitive impairment and is considered one of the most robust risk factors for Alzheimer’s disease (AD)." (PMID 31572165, 2019). "Taken together, the cognitive impairment of ApoE-KO mice is tightly associated with increased tau pathology including hyperphosphorylation, paired helical filament formation and cleavage by increased active-AEP in hippocampus." (PMID 30337867, 2018). "An association between this isoform and age of onset of temporal lobe epilepsy was found in several studies; also, the APOE-ε4 allele has been associated with cognitive impairment in epileptic patients." (PMID 30405395, 2018). "While both APOE genotype and obesity increase cognitive deficits and AD risk individually, few studies have investigated their combined effects." (PMID 30586872, 2018).
Cognitive impairment (continued). "As previously reported in the literature, AD genetic risk, as represented by APOE ε4+ genotypes predicted membership in the cognitive impairment group, in the context of the CN benchmark." (PMID 30333744, 2018). "The presence of truncated apoE within Lewy bodies is significant as these intraneuronal structures are the major pathological markers of PD and are associated with cognitive impairment in PD and DLB." (PMID 30272057, 2018). "APOE has previously been associated with cognitive impairment in PD patients but APOE effect on PD risk is still controversial." (PMID 29692703, 2018). "In fact, cognitive impairment has been reported after lorazepam treatment in patients with higher risk for AD (APOE-ε4 allele carriers)." (PMID 29755512, 2018). "Evidence has stated that ApoE ε4 and vascular risk factors combined aggravate cognitive impairment and their assessment can help in the understanding of the progression of MCI to AD." (PMID 32341958, 2018). "Additional experimental studies are required to explore the mechanism that ApoE genotype modifies the risk for cognitive impairment in aging subjects with T2DM." (PMID 29896424, 2018). "It has been demonstrated that aging, family history of cognitive impairment, low levels of physical activity, less education, and the presence of epsilon 4 allele of the apolipoprotein E (APOE ε4) gene are major risk factors of cognitive impairment." (PMID 29476112, 2018). "Recent studies have suggested that several biomarkers including blood apolipoprotein E ɛ4 (ApoE4) genotype, cerebrospinal fluid (CSF) Aβ1–42 (lower) and tau (higher) have been associated with cognitive impairment in PD in cross sectional studies." (PMID 30338062, 2018). "In summary, we have established a causal role of chronic hypoperfusive state and cognitive impairment in an ApoE-KO mouse model that faithfully replicate the atherosclerotic vascular pathology." (PMID 30337867, 2018). "That is, increased susceptibility of cognitive deficit can be secondary to poor repair mechanisms associated with APOE-KO/APOE4 knock-in in the presence of a proinflammatory response." (PMID 29209169, 2017). "α-synuclein expression and genetic polymorphisms of Apolipoprotein E (ApoE) have been associated with the presence of cognitive impairment in PD although data have been inconsistent." (PMID 29326545, 2017). "A detailed analysis of correctly and incorrectly classified subjects highlighted age associations in other factors: ApoE genotype, global cognitive impairment and gender." (PMID 26440606, 2016). "Another study where TBI patients underwent minimental state examination, apolipoprotein E genotyping, and amyloid-PET found an increase of amyloid accumulation and allele frequency of APOE4 in the mild TBI patients with cognitive impairment." (PMID 27630777, 2016). "There has been some investigation regarding the contribution of apolipoprotein (ApoE) ɛ4 allele and its association with cognitive impairment poststroke and overall disease outcome." (PMID 27895004, 2016). "Other prospective studies also confirm a close association among depression, APOE genotype and mild cognitive impairment." (PMID 27406263, 2016). "The contribution of genetic factors such as the presence of apolipoprotein (ApoE) ɛ4 allele and its association with cognitive impairment poststroke remains inconclusive, particularly in Middle Eastern regions." (PMID 27895004, 2016). "As expected, the analyses showed that the presence of APOE-4 alleles led to an accelerated trajectory of progression to severe global cognitive impairment." (PMID 26221415, 2015). "Meantime, previous studies have showed that the presence of ApoE ε4 allele was associated with smaller hippocampal volumes in women than in men in mild cognitive impairment (MCI) and AD." (PMID 26538817, 2015). "High levels of β-amyloid (Aβ) in the brain and carriage of the APOE ε4 allele have each been linked to cognitive impairment in cognitively normal (CN) older adults." (PMID 26430784, 2015).